MTERF1 (mitochondrial transcription termination factor 1)
Description:
Transcription termination factor. Binds to a 28 bp region within the tRNA(Leu(uur)) gene at a position immediately adjacent to and downstream of the 16S rRNA gene; this region comprises a tridecamer sequence critical for directing accurate termination. Binds DNA along the major grove and promotes DNA bending and partial unwinding. Promotes base flipping. Transcription termination activity appears to be polarized with highest specificity for transcripts initiated on the light strand.
Synonyms: mTERF
Tractability: PROTAC: ubiquitination databases record sites on it; its protein half-life has been measured.
Gene: Protein-coding gene on chromosome 7 (91,692,008 to 91,880,727, reverse strand). Ensembl gene ENSG00000127989.
Subcellular location: Mitochondrion
Subcellular location (Human Protein Atlas): Mitochondria
Pathways (Reactome):
Gene expression (Transcription): Mitochondrial transcription termination
Organelle biogenesis and maintenance: Transcriptional activation of mitochondrial biogenesis
Gene Ontology:
Molecular function: double-stranded DNA binding; protein binding; RNA binding; nucleic acid binding
Biological process: DNA geometric change; DNA-templated transcription termination; termination of mitochondrial transcription
Cellular component: mitochondrial nucleoid; mitochondrion; mitochondrial matrix
Genetic constraint (gnomAD): Loss-of-function variants: 29 observed, 32.81 expected, observed/expected ratio (o/e) 0.88, 90% interval 0.66 to 1.21. The upper end of that interval is the gene's LOEUF score, 1.21, which puts it in group 5 of 6, group 1 being the genes least tolerant of losing a copy. Missense variants: 500 observed, 495.37 expected, observed/expected ratio (o/e) 1.01, 90% interval 0.94 to 1.09. Synonymous variants: 152 observed, 173.67 expected, observed/expected ratio (o/e) 0.88, 90% interval 0.77 to 1.
Homologues: Orthologues: chimpanzee MTERF1 (99% identical), chimpanzee MTERF1 (96% identical), rabbit MTERF1 (83% identical), macaque MTERF1 (82% identical), pig MTERF1 (80% identical), dog MTERF1 (80% identical), guinea pig MTERF1 (78% identical), mouse Mterf1b (71% identical), rat Mterf1 (71% identical), mouse Mterf1a (71% identical), tropical clawed frog mterf1 (20% identical), Drosophila melanogaster mTTF (15% identical). Paralogues in human: MTERF2 (25% identical).
Diseases named in the same sentence as MTERF1 in open-access papers:
MTERF1 is named in the same sentence as 15 diseases in open-access papers, as found by Europe PMC text mining. Sharing a sentence is not in itself a finding about the gene and the disease. The quoted sentences say what the papers report.
colorectal cancer (2 papers, 2022 to 2024). A primary or metastatic malignant neoplasm that affects the colon or rectum. "Overexpression of MTERF1 in colorectal cancer (CRC) promotes cell proliferation, migration, invasion, and tumor formation." (PMID 38589371, 2024). "To further confirm the impact of MTERF1 on OXPHOS, we measured the oxygen consumption rate (OCR) of colorectal cancer cells." (PMID 36293209, 2022). "However, the molecular mechanism of MTERF1 in colorectal cancer (CRC) remains largely unknown." (PMID 36293209, 2022). "Additionally, MTERF1 regulates the AMPK/mTOR signaling pathway, leading to increased replication, transcription, and protein synthesis of mitochondrial DNA (mtDNA) in colorectal cancer cells." (PMID 38589371, 2024). "Here, we found that MTERF1 promoted mtDNA replication, transcription and improved the mitochondrial crista density, mitochondrial membrane potential, mitochondrial ATP production, oxygen consumption rate (OCR), and ROS production in colorectal cancer cells." (PMID 36293209, 2022). "Mechanistically, we revealed that MTERF1 regulates the AMPK/mTOR signaling pathway in cancerous cell lines, and we also confirmed the involvement of the AMPK/mTOR signaling pathway in both xenograft tumor tissues and colorectal cancer tissues." (PMID 36293209, 2022).
MELAS (2 papers, 2012 to 2020). "Mutations in the MTERF1 DNA-binding sequence lead to a spectrum of diseases under the syndrome MELAS (mitochondrial myopathy, encephalomyopathy, lactic acidosis, and stroke-like episodes) with devastating neuromuscular consequences." (PMID 33127643, 2020). "The connections between the MELAS-associated mutations and MTERF1 function have been clearly shown only in vitro." (PMID 33127643, 2020).
colon adenocarcinoma (1 paper, 2017). "Validation of these regions in the TCGA colon adenocarcinoma data identified a signature of 4 genes; ELOVL5, FAM127B, MTERF1 and ZNF606, which are downregulated in hypermethylated tumors." (PMID 28931069, 2017).
colon cancer (1 paper, 2022). "Here, we found that MTERF1 expression was significantly increased in colon cancer tissues compared with normal colorectal tissue by Western blotting, immunohistochemistry, and tissue microarrays (TMA)." (PMID 36293209, 2022).
COVID-19 (1 paper, 2026). A disease caused by infection with severe acute respiratory syndrome coronavirus 2. "Gene-level association analysis revealed MTERF1, TUFT1 (encoding Tuftelin1), and RETSAT (encoding retinol saturase) as the most significantly associated genes, all enriched for LoFs in patients with COVID-19." (PMID 41500120, 2026).
diabetes (1 paper, 2022). "However, a high expression level of MTERF1 protein was not correlated with patient age or sex, hypertension, diabetes, tumor size, ER expression, or PR expression in CRC (p > 0.05)." (PMID 36293209, 2022).
gastric adenocarcinoma (1 paper, 2021). "The average promoter methylation and mRNA expression levels of GNAS and MTERF1 were retrieved from 372 gastric adenocarcinoma cases." (PMID 35003353, 2021).
H.pylori (1 paper, 2021). "Depending on our previous genome-wide methylation profiles prior to and after anti-H.pylori treatment, the present study further validated that GNAS and MTERF1 methylation levels in blood leukocyte and gastric mucosa are correlated, and may be affected by H.pylori infection." (PMID 35003353, 2021).
cancer (3 papers, 2022 to 2025). A tumor composed of atypical neoplastic, often pleomorphic cells that invade other tissues. "Recent studies have also shown that MTERF1 causes gene amplification in a variety of solid tumors, and its abnormal protein expression may be involved in the development and metastasis of malignant tumors." (PMID 36293209, 2022). "To investigate the expression of MTERF1 in CRC, we first performed Western blotting and immunohistochemistry (IHC) analyses to evaluate the protein expression profiles of MTERF1 between cancer and normal tissues." (PMID 36293209, 2022). "The results showed that the expression of MTERF1 in CRC tissues was significantly higher than that in adjacent cancers." (PMID 36293209, 2022). "MTERF1 is a key regulator of mammalian mtDNA transcription and replication, and it plays a significant role in the regulation of cancer cell proliferation." (PMID 36293209, 2022). "Upregulated expression of MTERF1 in CRC cells could cause higher cell division and enhance migration and invasion of cancer cells to form tumors." (PMID 41403952, 2025). "The MTERF family includes MTERF1, MTERF2, MTERF3, and MTERF4 that have roles in the pathogenesis of various cancer types." (PMID 38324544, 2024). "Additionally, MTERF1 overexpression reduces ROS production, further enhancing mitochondrial activity for OXPHOS and contributing to cancer progression." (PMID 41403952, 2025).
tumor (3 papers, 2010 to 2022). "Subsequently, we extracted total proteins from the xenograft tumor and verified the overexpression and inhibition efficiency of MTERF1 in xenograft tumors." (PMID 36293209, 2022). "Knockdown of MTERF1 in HCT116 cells dramatically retarded tumor weights and volumes compared to scrambled shRNA-transformed cells." (PMID 36293209, 2022). "Our results showed that the tumor sizes in the MTERF1 overexpression group were significantly larger than those in the control group." (PMID 36293209, 2022). "In summary, MTERF1 expression promoted tumor formation in vivo." (PMID 36293209, 2022). "In addition, IHC staining for Ki67 in xenograft tumor tissues showed that MTERF1 indeed promoted cancerous cell proliferation in vivo." (PMID 36293209, 2022). "12S rRNA is essential for mitochondrial ribosome assembly, suggesting that MTERF1 knockdown could potentially increase mitochondrial ribosome assembly, giving a growth advantage to the tumor cells." (PMID 28931069, 2017). "Overexpression of MTERF1 in the HT29 cell promoted cell proliferation, migration, invasion, and xenograft tumor formation, whereas knockdown of MTERF1 in HCT116 cells appeared to be the opposite phenotype to HT29 cells." (PMID 36293209, 2022). "Overall, the transcriptional downregulation of ELOVL5, MTERF1 and ZNF606 shows potentially beneficial effect for the tumor cells." (PMID 28931069, 2017). "Compared with the adjacent tissues, MTERF1 was highly expressed, p-AMPK was suppressed, p-mTOR was increased, and the downstream effector proteins p-mTOR, P70S6K, and 4E-BP1 were phosphorylated in tumor tissues." (PMID 36293209, 2022).
respiratory disorders (1 paper, 2021). "The m.3243A>G mutation occurs in the mtDNA binding site of MTERF1, which leads to a decrease in MTERF1 affinity, resulting in mitochondrial protein synthesis defects and respiratory disorders." (PMID 34277617, 2021).
MTERF1 also shares sentences with these, for which no sentence is quoted: Hypertension (1 paper); infection (1); ischemia (1); MELAS syndrome (1).